LINC01089 (long independently transcribed non-coding RNA 1089)
Diseases named in the same sentence as LINC01089 in open-access papers (continued):
Sharing a sentence is not in itself a finding about the gene and the disease.
tumor (14 papers, 2016 to 2025). "The decreased levels of LINC01089 are significantly associated with larger tumor sizes, higher T staging, and lymph node metastasis." (PMID 39334363, 2024). "Low expression level of LINC01089 in GC tissues was markedly linked to larger tumor size, higher T stage, as well as lymphatic metastasis of the patients." (PMID 33088215, 2020). "It was found that LINC01089 was markedly under-expressed in GC and the low expression of LINC01089 was associated with tumor size, T stage, as well as lymphatic metastasis." (PMID 33088215, 2020). "The results suggested that low expression of LINC01089 may be associated with tumor proliferation and migration." (PMID 36306007, 2022). "Moreover, it was demonstrated that low expression of LINC01089 was markedly linked to tumor size, T stage, as well as lymphatic metastasis." (PMID 33088215, 2020). "By regulating this pathway, LINC01089 significantly influences tumor invasiveness and chemoresistance, making it a promising therapeutic target in the treatment of SCLC." (PMID 39334363, 2024). "As a tumor suppressor, LINC01089 inhibits EMT in HCC cells by sequestering miR-665, thereby reducing resistance to sorafenib." (PMID 39334363, 2024). "In summary, modulating LINC01089 expression can significantly affect tumor cell sensitivity and resistance to chemotherapeutic drugs." (PMID 39334363, 2024). "The role of LINC01089 in regulating tumor cell migration and EMT makes it a potential therapeutic target." (PMID 39334363, 2024). "LINC01089 plays a crucial role in regulating tumor cell migration and epithelial-mesenchymal transition (EMT)." (PMID 39334363, 2024). "Animal experiments further confirmed this, with tumor volumes in the LINC01089 knockdown group being significantly higher than those in the control group after chemotherapy, clearly illustrating LINC01089’s role in inhibiting tumor cell chemoresistance." (PMID 39334363, 2024). "Lower LINC01089 expression was correlated with higher tumor stage and regional lymph node metastasis." (PMID 36306007, 2022). "Thereafter, subcutaneous injection of shLINC01089-A549 into nude mice, for establishment of tumor proliferation, showed that depletion of LINC01089 promoted tumorigenesis in vivo." (PMID 33282723, 2020). "Changes in LINC01089 expression can markedly influence tumor cell migration and EMT processes." (PMID 39334363, 2024). "Overall, LINC01089 is a significant contributor to tumor formation." (PMID 39334363, 2024). "Additionally, LINC01089 plays a significant role in various tumor gene regulatory processes by acting as a modular scaffold, interacting with heterogeneous nuclear ribonucleoprotein M (hnRNPM), and influencing downstream molecular mediators." (PMID 39334363, 2024). "Modulating LINC01089 expression could inhibit tumor migration and metastasis, improving treatment efficacy." (PMID 39334363, 2024). "Evidence suggests that LINC01089 exhibits a dual role in HCC tumor tissues." (PMID 39334363, 2024). "LINC01089 has been shown to regulate the cell cycle during tumor development." (PMID 39334363, 2024). "LINC01089 has shown tumor-suppressive effects in several cancer types." (PMID 39791702, 2024). "LINC01089 exerts a tumor suppressor effect by up-regulating the level of FBLN5." (PMID 36306007, 2022). "Additionally, lower LINC01089 expression was related to female patients, greater tumor size, and the metastasis of regional lymph nodes." (PMID 36306007, 2022). "In summary, our results indicate that LINC01089 is a tumor suppressor in NSCLC." (PMID 33282723, 2020). "Besides, LINC01089 overexpression could lead to a suppressed tumor growth as well as a decreased tumor weight." (PMID 34281560, 2021). "Subsequently, an analysis of LINC01089 on cell proliferation and migration in NSCLC in vitro and in mouse tumor formation revealed that LINC01089 knockdown promoted the cell proliferation and the migration as well as tumor formation in NSCLC." (PMID 33282723, 2020).
tumor (continued). "In this study, we report the downregulation of LINC01089 in non-small cell lung cancer (NSCLC) samples, relative to adjacent non-tumor tissues, and demonstrate its role in the inhibition of proliferation, migration, and epithelial–mesenchymal transition (EMT) of NSCLC cells." (PMID 33282723, 2020).
cancer (8 papers, 2016 to 2024). A tumor composed of atypical neoplastic, often pleomorphic cells that invade other tissues. "Future research should delve deeper into the specific mechanisms by which LINC01089 functions in these cancers to elucidate its role in cancer progression and to advance related diagnostic and therapeutic strategies." (PMID 39334363, 2024). "Collectively, these findings underscore the pivotal role of LINC01089 in cancer biology and its potential as a diagnostic and prognostic marker." (PMID 39334363, 2024). "In this review, we systematically explore the functions of LINC01089 in human cancers through bioinformatics analysis, clinical studies, animal models, and fundamental experimental research." (PMID 39334363, 2024). "LINC01089 is a prime example of a long non-coding RNA that plays a pivotal role in the progression of human cancers." (PMID 39334363, 2024). "This downregulation across various cancers suggests that LINC01089 may serve as an important biomarker and potential therapeutic target." (PMID 39334363, 2024). "LINC01089 plays a crucial role in tumorigenesis and cancer progression." (PMID 39334363, 2024). "The expression levels of LINC01089 exhibit significant variation across 20 different cancer types." (PMID 39334363, 2024). "The differential expression suggests that LINC01089 may have distinct biological functions across various cancer types." (PMID 39334363, 2024). "Recent studies have shown that LINC01089 exerts an inhibitory effect on some cancers." (PMID 33088215, 2020). "This indicates that LINC01089 expression may influence cancer progression and patient prognosis." (PMID 39334363, 2024). "Thus, the interaction between LINC01089 and TET1 plays a crucial role in regulating cancer progression." (PMID 39334363, 2024). "Previous studies have correlated cancer-related functions with AL360004.1, LINC00173, LINC01089 and LINC00115; however, none of them have been linked to the pathogenesis of AIS." (PMID 35401659, 2022).
LINC01089 also shares sentences with these, for which no sentence is quoted: acute myeloid leukaemia (1 paper); breast tumors (1); infection (1); osteosarcoma (1); papillary thyroid carcinoma (1); pulmonary arterial hypertension (1); viral infections (1).